CD4 (CD4 molecule)
Diseases named in the same sentence as CD4 in open-access papers (continued):
Sharing a sentence is not in itself a finding about the gene and the disease.
lymphoma (continued). "In addition, it may have similar functions to MDV viral IL8 (vIL-8) in the hinge of infection from B to T lymphocytes, which promotes lymphoma formation through the subsequent recruitment of CD4+ T cells." (PMID 36680047, 2022). "It is possible that the lymphoma and/or the chemotherapy used to treat the lymphoma, combined with the age of the donor (age 73), could have reduced the overall number of CD4+ T cell clones, which could also have affected the number and relative sizes of the infected clones." (PMID 36044447, 2022). "Similar to lymphomas, they may be CD4+, CD8+ or double positive." (PMID 35951029, 2022). "Noteworthy, EBNA-1 specific cytotoxic CD4 T cells are decreased in patients with post-transplant lymphoproliferative disorders, in some pediatric forms of Burkitt lymphoma, in EBV-positive lymphoma, in lymphomas associated with HIV infection, and in lymphoma infiltrating the central nervous system." (PMID 34867935, 2021). "Interestingly, Berquam-Vrieze and colleagues compared subsets of SB-induced mouse lymphoma and found that the CD4-Cre (most differentiated cell of origin) lymphoma matched the expression patterns of human ETP-ALL, a subtype of T-ALL defined by expression patterns of early T-cell precursors." (PMID 32050713, 2020). "Thus, EBV-infected B cells with stringent latency types that are not transforming in vitro may receive growth and survival factors from CD4 T cells and/or collagen in the tumor microenvironment that allow these cells to induce lymphomas in vivo." (PMID 32542010, 2020). "However, as might be expected based on previous research in koalas, the KoRV-A- and B-positive koala with lymphoma that died in this study showed a markedly decreased CD4:CD8b ratio and markedly increased IL-10 expression." (PMID 33316950, 2020). "Moreover, 7 of 11 (63.3%) patients with the lymphoma pattern expressed more CD8 than CD4." (PMID 31101882, 2019). "Lower frequencies of naïve (p = 0.022) and central memory (p = 0.034) CD4+ T cells were found in HIV+ patients with AIDS-associated infections than in those who did not present them; as previously reported, this result was found in HIV+ patients at stage 3 and with lymphoma." (PMID 30337929, 2018). "However, LAG-3 was highly expressed on CD4+ or CD8+ T cells from lymphoma biopsies." (PMID 28977875, 2017). "Adult T-cell leukemia/lymphoma (ATLL) is an aggressive lymphoma associated with human T-lymphotrophic virus 1 (HTLV1) infection, and ATLL cells frequently express several molecules that are characteristic of Tregs, notably CD4, CD25, and the transcription factor FOXP3." (PMID 22151904, 2011). "In our setting, we have shown in this study that IRF4 upregulates both PD-L1 in EBV lymphoma cells and PD1 in co-cultured CD4+ T cells, in agreement with its oncogenic role in EBV+ lymphomas." (PMID 40733503, 2025). "The frequency of CD3 + T cells in lymphocytes and CD4 + and CD8 + subsets within CD3 + T cells varied between lymphoma patients." (PMID 40630518, 2025). "The degree of immunosuppression, reflected in nadir CD4 counts and HIV staging, expresses the resources of immune recovery under ART and influences not only lymphoma aggressiveness but also the ability to complete treatment." (PMID 40606992, 2025). "While cART improves immune function by increasing CD4+ T-cells and reducing viral load, chronic immune activation persists, particularly in CD8+ T-cells, driving B-cell dysregulation and promoting lymphoma development." (PMID 41148820, 2025). "The elevated proportion of CD4+FoxP3+PD-1+ Tregs in HIV-positive pre-NHL individuals likely reflects an adaptive response to chronic inflammation but may also serve as a mechanism that hampers effective HIV control, increasing the risk of lymphoma development in pre-NHL states." (PMID 41148820, 2025).
lymphoma (continued). "By cluster analysis, the EM subsets were further divided, revealing that CD4 + EM2 T cells (cluster 8), which express CD25, were enriched in lymphoma patients, particularly in the MON group (p = 0.0019)." (PMID 40630518, 2025). "Tim-3+ ECs modulate the T cell response to lymphoma surrogate antigens by inhibiting CD4+ T cell activation and Th1 polarization in an IL-6-STAT3-dependent way, thus promoting lymphoma onset, growth, and dissemination." (PMID 39781467, 2025). "Patients with lymphoma had the highest rate of HIV positivity (61.5%, n = 8/13), and almost all were on ART and virally suppressed with a median CD4 count of 278 cells/mm3 (IQR 104–726)." (PMID 41200369, 2025). "In this study, we observed an increase in the percentage of a Treg-like phenotype expressing mTGF-β and CD4 in PBMCs of MDV-infected chickens as previously reported, likely reflecting the expansion of lymphoma cells." (PMID 40673706, 2025). "We propose that NKG7 exerts the same function in cytotoxic CD4+ T cells including TFK cells, leading to GZMK-mediated complement activation or GZMB-mediated activation-induced cell death of target – possibly lymphoma – cells." (PMID 41030456, 2025). "Age correlated negatively with levels of naïve CD4 + and CD8 + T cells in lymphoma patients (r=−0.34, p = 0.0153, r=−0.59, p < 0.0001)." (PMID 40630518, 2025). "Comparative analysis revealed that in MALT lymphoma, CD4+ naive T-cells predominantly differentiated into Tfh cells, whereas in IgG4-ROD lymphoma, they mainly differentiated into Treg cells." (PMID 40078987, 2025). "The expression of T cell antigens, including CD2, CD4, CD5, CD7, and monocytic antigens, has also been reported in B-lymphoblastic leukemia/lymphoma." (PMID 40227608, 2025). "We found that GC-derived lymphomas contain a sizable number of PD-1+CXCR5+ TFK cells among the TFH cells and among the cytotoxic CD4+ T cells, respectively." (PMID 41030456, 2025). "CD4 + EM3 T cells (cluster 9), expressing ICOS and PD-1, were enriched in lymphoma patients, except those who had received CT alone." (PMID 40630518, 2025). "The one well-responding lymphoma patient, however, exhibited especially high numbers of CD3+/CD4+ helper T-cell- and low CD3+/HLA-DR+ activated T-cell numbers." (PMID 41050077, 2025). "Next, to determine the spatial distribution of T cells, we performed CD4 and CD8 immunohistochemistry on late-stage lymphomas." (PMID 38570506, 2024). "This was similarly observed with tightly packed CD4 + and CD8 + T cells in lymphoma tissues only, and we termed these cells “T Cells” in downstream analyses." (PMID 38311785, 2024). "In most of haematological malignancies, such as lymphoma and in solid tumours, such as NSCLC, cancer cells express MHC II and become direct targets for CD4+ T cells." (PMID 38541208, 2024). "Immunophenotyping of the tumours from sick p21−/−Zmat3−/−, Zmat3−/− and p21−/− mice confirmed that these lymphomas were all of T lymphoid origin expressing THY1 and variable expression of CD4 and CD8." (PMID 38110554, 2024). "And considered CAR T cells directed against murine CD4 as a promising strategy for AITL patients since ex vivo generated anti-CD4CAR NK or T cells were able to eliminate human T-cell leukemia and lymphoma in preclinical mouse models." (PMID 39272178, 2024). "B cell depletion and lower CD4 and CD8 counts were found in patients under treatment or recently treated for lymphoma." (PMID 39902042, 2024). "IHC studies showed the lymphoma cells to be positive for CD3 (8/8, 100%), CD4 (7/8, 87.5%), CD7 (2/3, 66%), and CD30 (20/21, 95%, median expression: 80%)." (PMID 38474383, 2024). "It has been described that MCL exhibits features of exhaustion, including high expression of PD-1 and TIGIT in both CD4 and CD8 T cells, as well as the presence of the corresponding ligands PD-L1, CD155 and CD112 in lymphoma cells and/or macrophages." (PMID 37031299, 2023).
lymphoma (continued). "The immunophenotypes of lymphoma in dogs is categorized according to the origin of B-and T-cells, with representative markers of CD21/CD79a and CD3/CD4/CD8 commonly used in dogs." (PMID 37908841, 2023). "Exhausted T cells dramatically increased in the CD3+CD4+ and CD3+CD8+ subpopulations in lymphoma-bearing animals." (PMID 37048617, 2023). "Among the T cells, one dog was identified as CD34+ and CD4-/CD8-, suggesting the possibility of precursor lymphoma." (PMID 37908841, 2023). "PD-1 molecule is expressed in activated both CD4-positive and CD8-positive T cells and also in natural killer (NK) cells, B-lymphoma cells (B cells), dendritic cells (DC), and activated monocytes." (PMID 37237922, 2023). "In patients with lymphoma and myeloma, the decrease of CD8 + cells following the chemotherapy was concomitant to the increase of TTV levels, whereas patients with low CD4 + cell count demonstrated TTV viremia significantly elevated." (PMID 36744144, 2023). "For lymphoma patients, there are a variety of potential targets, such as T-cell markers (CD3, CD4, and CD8), B-cell markers (CD19 or CD20), and immune checkpoints (PD-1, PD-L1, or CTLA-4)." (PMID 37189191, 2023). "The phenotypes of lymphoma cells from Lck-Tax transgenic mice, which were transferred into severe combined immunodeficiency (SCID) mice, were pre-T cells (CD4−/CD8−/CD44+/CD25+ and cytosolic CD3+)." (PMID 37511495, 2023). "Since most TCL are CD4+, anti-CD4 CAR-T treatment has also been proposed for these lymphomas (NCT03829540)." (PMID 36936927, 2023). "A lot of studies reported the lower amount of CD4 T cells and CD8 T cells in the lymphoma microenvironment correlated with poor survival." (PMID 38155967, 2023). "Nodal TFH lymphomas share phenotypic and gene expression similarities with normal T follicular helper (TFH) cells, a CD4+ T cell subset that promotes germinal center B cell differentiation." (PMID 37841428, 2023). "An inguinal LN biopsy appeared as a tumor-cell-rich AITL, with abundant lymphoma cells, clear cytoplasm, and arborizing vessels, and expressed a TFH immunophenotype (CD3+, CD5+, CD7-, CD4+, strong ICOS, and PD1), though CD25 and FOXP3 were also positive." (PMID 37500795, 2023). "Most cases of MF have the phenotype of T-helper lymphocytes (CD3+/CD4+), while CD8+ lymphomas are relatively rare." (PMID 37829962, 2023). "Conventional CD4+CD127loFoxP3+ Tregs and unconventional CD4+CD127hiFoxP3+ Tregs expressing cytotoxicity markers CD107 and FasL have been described in lymphoma and CLL patients." (PMID 35979372, 2022). "Although CD4/CD8 respective proportions and function were reported as predictors of patient outcomes in cancer, studies were often unclear or contradictory in lymphomas." (PMID 35083113, 2022). "Few T-cell phenotypes (positive betaF1 and TCR-γ), aberrant expression of CD4 and CD8, and focal CD30 positivity were also present in lymphoma cells." (PMID 36135102, 2022). "Murine tumors displayed the phenotypic diversity observed in ALK+ ALCL patients, including CD4+ and CD8+ lymphomas." (PMID 35246138, 2022). "The recently detected DNMT3A mutation being reported by the French lymphoma study group in one single case of their series of CD4+ lymphoproliferation has hitherto not been described in PCFBCL, and thus might represent a discriminatory molecular feature if validated in further studies." (PMID 36358692, 2022). "Consistent with previous findings, we found that the HSP90 inhibitor downregulated CD4 and CD8 surface expression on activated T cells in healthy controls and lymphoma patients." (PMID 36359267, 2022). "While KS is one of the AIDS-defining illnesses seen in immunocompromised patients having low CD4 count, PEL is a rare and distinct subset of AIDS-related lymphoma." (PMID 35842670, 2022).
lymphoma (continued). "Many investigators studying T-cell subsets in lymphoma and CLL have utilized variations of the widely accepted CD4+CD25hiCD127-/loFoxP3+ flow cytometry gating strategy to identify Tregs, where CD127+/hi cells representing memory T cells are excluded." (PMID 35979372, 2022). "PI3K-AKT-mTOR signaling genes, which are frequently up-regulated in lymphomas including ATLL, were primarily up-regulated in CD4 Tem and CD4 proliferating T-cells." (PMID 35464471, 2022). "Based on these results, we conclude that the effector CD4+ T cells activated by LMP1/2A+ B lymphoma cells contain CD4+ CTLs that recognize and kill lymphoma cells in an MHC-II-specific manner, while CD8+ CTLs kill target cells dependent on MHC-I as expected." (PMID 36077655, 2022). "A univariate analysis demonstrated that the age, B symptoms, treatment status, IPI, pathological stage, ECOG PS, CD4+ cell count, β2 microglobulin, LDH, and CONUT score were prognostic factors for patients with HIV infection-related lymphoma (p < 0.05)." (PMID 36438738, 2022). "In the previous study, MHC-dependent cytotoxicity of both effector CD4+ T and CD8+ T cells activated by LMP1-expressing B lymphoma cells was shown against those lymphoma cells." (PMID 36077655, 2022). "This likely represents a critical cancer immunoediting escape mechanism used by lymphoma cells to evade the effector activity of lymphoma-specific CD8+ and CD4+ T cells." (PMID 33842331, 2021). "Conversely, loss of CTSS activity in aggressive mouse lymphoma xenograft restrain lymphoma growth by recruiting and enhancing CD8+ T cells cytotoxic activity while impairing communication with CD4+ TFH cells." (PMID 34335584, 2021). "When compared with WT, WASpL272P CD4+ and CD8+ T cells had a similar capacity to kill A20 lymphoma cells via TCR stimulation." (PMID 33621210, 2021). "This disease was initially described in 2011 in two males showing recurrent pulmonary infections, low CD4+ T cells, and EBV-induced LPD and lymphoma." (PMID 34638238, 2021). "Interestingly, ADCT-301 treatment in preclinical models and in patients with advanced solid tumors or lymphomas resulted in transient reduction of Treg cells, while CD4+ and CD8+ T cells were unaffected, which might enhance ADCT-301-mediated anti-tumor activity." (PMID 34552066, 2021). "A more recent study considered as inclusion criteria to define TCL a lymph node with a cytology/histopathology suggestive of lymphoma together with a positive reactivity to CD3, or CD4, CD8, in more than 10% of large lymphoid cells." (PMID 33969027, 2021). "All lymphoma patients were tested for CD3, CD4, CD8, CD11a, CD5, CD21, CD34, CD79acy and MHCII expression." (PMID 34268346, 2021). "Lymphoma Ig neoantigen-specific CD8+ and CD4+ T cells were identified in the PB over 2 years after vaccination completion/vaccine-primed lymphocyte reinfusion." (PMID 35008305, 2021). "In contrast, the loss of function mutations in the TNFRSF14 gene leads to B-cell autonomous activation as well as extrinsic activation of the lymphoma microenvironment through B and T-lymphocyte attenuator (BTLA attenuator) located on CD4+ T-helper cells." (PMID 34275438, 2021). "In vivo, IT CMP-001 extended the survival of Balb/c mice bearing A20 lymphoma, which constitutively expresses PD-L1, and regression of both injected and non-injected tumors was dependent on whether mice could produce anti-Qβ antibody and whether CD4+ or CD8+ T cells existed." (PMID 35008305, 2021). "In mouse models of lymphoma, CAR-T cells derived from TN and TCM cells were shown to be more efficacious than those from than TEM cells due to superior cytokine production of CD4+ T cells and cytotoxicity of CD8+ T cells." (PMID 33013907, 2020). "Consistent with the phenotype of T-lymphoma, the distribution of T-lymphocyte subsets was altered in the MYCON cohort with an increase in percentages of immature CD4+CD8+ double positive (DP) CD3+ T-lymphoblasts as compared to normal mice." (PMID 32503978, 2020).
lymphoma (continued). "Lymphoma cells in all 11 ATLL patients were CD3+, CD25+, and of those, nine (100%) were CD194+ (CCR4) and nine (82%) were CD4+." (PMID 33087157, 2020). "Double positive CD4+CD8+ T-cell is by far the most represented phenotype in feline mediastinal lymphomas in our caseload (eight cases, 67% of lymphoma cases), whereas it is relatively rare in dogs and most mediastinal lymphoma exhibit CD4+ T-cell phenotype." (PMID 32903608, 2020). "The percentage of CD4+CD8+ cells was statistically higher in double positive lymphoma (mean = 85.9, s.d. = 12.3, median = 85.5, range 67.7–99.8) than in non-lymphoma samples (mean = 46.5, s.d. = 29.2, median = 48.4, range 2.7–78.8) (P = 0.006)." (PMID 32903608, 2020). "Twenty-nine percent of patients were HIV-infected (n = 47): with a median CD4 count of 143 cells/mm3 (IQR, 69–274) and 61% on antiretroviral therapy at the time of lymphoma diagnosis." (PMID 31023278, 2019). "ACs, CD4-positive samples and smoldering patients showed significantly higher TCR diversity compared with chronic, acute and lymphoma subtypes." (PMID 31069115, 2019). "In these lymphoma samples, significantly higher expression of CTLA-4 was observed on CD4+ lymphocytes obtained from PBMCs." (PMID 30040869, 2018). "In vivo, CD4+ T cells co-expressing a B7H6-specific CAR and T-bet improved the survival of RMA-B7H6 lymphoma-bearing mice." (PMID 29515240, 2018). "A similar analysis on CD4+CXCR5+CCR6+ (cTfh1/17 and cTfh17) populations also confirms increased PD1 expression in lymphoma patients." (PMID 29293620, 2018). "Reduction of EBV-specific IL-2+ CD4+ and CD8+ T cells was found in HIV+ patients in stages 2, 3, and with lymphoma, which was evident of the first stages of T-cell exhaustion." (PMID 30337929, 2018). "Similar to T-cell leukemia/lymphoma cell lines, the level of UBR5 RNA was decreased in all PBL clones compared to naïve and memory CD4 T-cells." (PMID 29441057, 2018). "Further studies on CD4+ and CD8+ T cells populations of lymphomas collected from co-infected chickens will help to understand the role and significance of these complex interactions in co-pathogenesis of CAV and MDV." (PMID 29988968, 2018). "Most Eμ‐MYC/Vav‐BFL1 mice also developed pre‐B lymphomas but a significant number (7 of 11 mice analysed) additionally developed CD19−B220+CD4+ progenitor cell lymphomas that have been described before for Eμ‐MYC/Eμ‐BCL2 mice." (PMID 29498802, 2018). "Similar to the primary lymphoma cells, MDV-transformed CD4+ T cell clone (clone 265L; generated from line P) expressed both membrane bound and intracellular TGF-beta, as demonstrated using flow cytometry and confocal microscopy, respectively." (PMID 29267390, 2017). "IHC confirmed that primary and disseminated tumor cells were of T-cell origin, based on positive staining for CD3, and that malignant cells were immature T cells, as they were CD4+CD8+ double positive (DP), similar to lymphoma cells in Lck-MyrAkt2 mice." (PMID 28122332, 2017). "Median CD4+ cell count and HIV-RNA at diagnosis of lymphoma in HIV-L were 232/mmc (IQR 132–417) and 2.34 log10 copies/ml (IQR 1.69–4.74), respectively." (PMID 29088223, 2017). "Lymphomas that develop in both Dnmt3aΔ/Δ and Dnmt3a+/- mice are exclusively CD8+CD4- mature T cell lymphomas." (PMID 27690235, 2016). "In contrast, lymphomas of similar size in EBV-infected animals treated with PD-1/CTLA-4 blockade had many more infiltrating CD8-positive and well as CD4-positive T cells, such that T cells often outnumbered the B cells in tumor infiltrates." (PMID 27186886, 2016). "Compared with normal controls (median, 0.656% of CD4+IFN-γ− T cells; range, 0.286–2.640%; n = 39), the frequency of circulating Th22 cells was significantly elevated in newly-diagnosed patients with lymphoma (1.350%; 0.124–5.230%; n = 47; P = 0.0053)." (PMID 27489357, 2016).